HMGB1 (high mobility group box 1)
Diseases named in the same sentence as HMGB1 in open-access papers (continued):
Sharing a sentence is not in itself a finding about the gene and the disease.
ischemia (continued). "During ischemia, a number of damage-associated molecule pattern (DAMP) proteins, such as S100B and high mobility group box-1 (HMGB1), are released from damaged tissues, and stimulate TLR4." (PMID 28222157, 2017). "Cell necrosis and apoptosis are hallmarks of ischemia reperfusion injury and release of danger signals (e.g, HMGB1, HSP and S100 proteins) following ischemic insult is a well-known event after ischemic tissue injury." (PMID 28832655, 2017). "Hepatocyte-specific HMGB1 deletion has been found to worsen the injury and inflammation in liver ischemia-reperfusion injury (IRI), highlighting a role for intracellular HMGB1 in cellular protection." (PMID 28382970, 2017). "We injected the HMGB1 neutralizing antibody using an infusion pump over the course of 5 min beginning 30 min prior to the onset of ischemia." (PMID 27544687, 2016). "This makes it seem unlikely that these cytokines and the HMGB1 that induces them are important in the evolution of a reversible episode of ischemia to an area of irreversible damage." (PMID 27544687, 2016). "Next, we performed an ELISA to measure HMGB1 levels in serum samples obtained 4 h after the onset of ischemia." (PMID 27544687, 2016). "In the present study in a rat in vivo model, the myocardial HMGB1 level increased significantly after 30 min ischemia and 48 h reperfusion." (PMID 25780465, 2015). "Pretreatment with atropine, however, did not affect the ability of electroacupuncture to inhibit myocardial HMGB1 expression after ischemia (Atro+PC6+IR vs. PC6+IR, p > 0.05)." (PMID 26499847, 2015). "We compared levels of myocardial HMGB1 expression and indices of ischemia-reperfusion injury between groups immediately after ischemia and after 24 h of reperfusion." (PMID 26499847, 2015). "Inhibition of HMGB1 significantly suppressed the expression of cleaved caspase-8 in ischemia retinal tissue." (PMID 26224068, 2015). "Hydrogen enriched saline treatment inhibited HMGB1 expression and release, reflecting a reduced local and systemic inflammatory response to hepatic ischemia reperfusion." (PMID 24410860, 2014). "We also measured serum HMGB1 levels and examined nuclear HMGB1 staining within the muscle tissue itself because we have previously reported that ischemia induces the mobilization and release of nuclear HMGB1 in myocytes." (PMID 24844636, 2014). "The effect of HMGB1 in animal models of cardiac ischemia has been previously examined in acute MI, ischemia/reperfusion injury and post-MI heart failure." (PMID 21731608, 2011). "MIF release, also detected by Western blot, followed a similar kinetic as HMGB1 release and was also released significantly higher upon mechanical stress compared to ischemia only." (PMID 21197406, 2010). "Neutrophil extracellular traps mediate cardiomyocyte ferroptosis via the Hippo-Yap pathway to exacerbate doxorubicin-induced cardiotoxicity, where HMGB1 acts as an iron apoptosis inducer by upregulating ferroptosis in astrocytes, thereby aggravating the acute injury after ischemia in the brain." (PMID 40495163, 2025). "Validated targets of miR-129-5p are CAMTA1 (calmodulin-binding transcription factor), indicating a role of calcium under this condition, SOX4 (regulation of Wnt pathway), GALNT1 (modifying glycan structures), EIF2C3 and HMGB1, which has been shown to protect against ischemia/reperfusion injury." (PMID 39201485, 2024). "Further investigation into the effects of EPA‐induced expression of HMOX‐1 and HMGB1 retention in other systems, including those modeling ischemia reperfusion injury, may reveal other novel protective effects." (PMID 38958135, 2024). "The NF‐κB p65, TLR4 and HMGB1 protein contents were markedly enhanced following ischemia." (PMID 37132060, 2023).
ischemia (continued). "Data from in vivo animal model experiments using chimeric mice strongly indicated that for the development of ischemic brain damage, RAGE expressed by immigrant macrophages is required, possibly for binding the HMGB1 released from necrotic cells in the ischemia core." (PMID 36421725, 2022). "Plasma HMGB1 rapidly increases and acts as a proinflammatory cytokine to activate microglia, aggravate excitotoxicity-induced neuronal death, and aggravate brain injury during the acute damaging phase of ischemia insult." (PMID 34372857, 2021). "Furthermore, studies have shown that HMGB1 are released rapidly after cerebral ischemia by astrocytes or 1 week after ischemia by microglia." (PMID 32245271, 2020). "An experimental model of CCH in a previous study demonstrated that the administration of anti-HMGB1 neutralizing antibody (Ab) at the acute stage of ischemia could reserve hippocampal neuronal death and improve cognitive impairment." (PMID 32245271, 2020). "The regulation of HMGB1 release or the neutralization of extracellular HMGB1 produces beneficial effects on brain injuries induced by ischemia, hemorrhage, trauma, epilepsy, and Alzheimer’s amyloidpathy in animal models and is associated with improvement of the neurological symptoms." (PMID 33321691, 2020). "However, following ischemia, HMGB1 can be passively released by necrotic cardiomyocytes or be actively generated by immune cells such as macrophages, monocytes, and dendritic cells." (PMID 31344138, 2019). "This role for HMGB-1 is supported by studies demonstrating that administration of monoclonal antibody to HMGB-1 protects against ischemia-induced BBB disruption in rats, and in humans anti-HMGB1 monoclonal antibody improves the BBB integrity of patients with Alzheimers disease." (PMID 30416436, 2018). "In addition, extracellular HMGB1 also acts on its target receptors on endothelial progenitor cells (EPCs) to promote peri-infarct angiogenesis which is related to ischemia/reperfusion-induced HT." (PMID 30139371, 2018). "Knockdown of nuclear HMGB1 expression dramatically reduced both the degree of nuclear-cytoplasmic translocation of HMGB1 during hepatic ischemia and of HMGB1 release after hepatic reperfusion, resulting in significant preservation of liver function and a marked reduction in pathological damage." (PMID 28382970, 2017). "However, HMGB1 has recently been found to be passively released by necrotic cardiomyocytes in response to ischemia and acts as an early mediator of inflammation following I/R injury." (PMID 28222157, 2017). "In addition, glycyrrhizin has been known as a selective inhibitor of high-mobility group box-1, a potent proangiogenic molecule, and it attenuated ischemia-induced retinal neovascularization in a mouse model." (PMID 29234364, 2017). "Anti-HMGB1 therapy would interrupt this cascade by neutralizing the extracellular HMGB1, thereby preventing inflammatory responses and strong vasospasm in the BA, and ultimately reducing the ischemia-induced brain damage and improving the neurological symptoms." (PMID 27883038, 2016). "The combination of chemical sympathectomy and electroacupuncture pretreatment inhibited HMGB1 expression immediately after ischemia to a greater extent than did electroacupuncture alone (GS+PC6+IR vs. PC6+IR, p = 0.023), and it also provided greater cardiac protection (p < 0.05)." (PMID 26499847, 2015). "In this study we found no support in the peripheral circulation for endothelial cell activation measured by soluble adhesion molecules or for an inflammatory response measured by HMGB1 levels within 2 hours after ischemia in patients undergoing knee surgery using spinal anesthesia." (PMID 25328284, 2014). "Moreover, the rats of the ischemia + CQ group had higher percentage of cells with the release of HMGB1 from the nuclei compared to that of the rats of the ischemia group." (PMID 23758862, 2013).
ischemia (continued). "We hypothesized that oxidation of HMGB1 may reduce its pro-inflammatory potential and could take place during prolonged ischemia and upon reperfusion." (PMID 22514737, 2012). "In addition to its role in mediating amplification of inflammation and angiogenesis, several studies demonstrated that extracellular HMGB1 can aggravate tissue damage in neuronal tissues after ischemia." (PMID 21850157, 2011). "The cytosolic HMGB1 level could be significantly increased and nuclear HMGB1 decreased after several CNS diseases including subarachnoid hemorrhage and ischemia, which suggested that the early cytosolic HMGB1 increase was predominantly due to the translocation of nuclear HMGB1." (PMID 40291503, 2025). "Also with regard to hepatic ischemia/reperfusion injury, it has been demonstrated that inhibition of the intrinsic pathway of apoptosis and autophagy was mediated partly through downregulation of HMGB1/TLR4/NF-κB axis." (PMID 29420582, 2018). "Therefore, treatment with anti-HMGB1 mAb may be an effective therapeutic strategy for SAH-induced vasospasm as well as ischemia-induced brain injury." (PMID 27883038, 2016). "In investigations regarding hepatic ischemia—reperfusion injury, Eritoran, a crucial TLR4 antagonist, mitigates liver inflammation and cellular impairment through the blockade of the HMGB1—TLR4 axis." (PMID 40877572, 2025). "HMGB1 mediates the secretion of MMP9, which is involved in early blood–brain barrier degradation and plasma leakage during ischemia via pericytes." (PMID 38740617, 2025). "Salvianolic acid D inhibited nucleoplasmic translocation of HMGB1 and its downstream TLR4/MyD88/NF-κB signaling, thereby attenuating ischemia–reperfusion brain injury." (PMID 38740617, 2025). "HMGB1 and cfDNA released from ischemic myocardium activated the intra-myocardial TLR9 – IFN-I inflammatory pathway during ischemia and extra-myocardial TLR9 – IFN-I inflammatory pathway during reperfusion." (PMID 36081846, 2022). "HMGB1 and cfDNA released from ischemic myocardium activated the intra-myocardial TLR9 – IFN-I inflammatory pathway during ischemia and the extra-myocardial TLR9 – IFN-I inflammatory pathway during reperfusion." (PMID 36081846, 2022). "MiR-183-5p enriched in Hemin-MSC-EXO, partially via regulation of the HMGB1/ERK pathway, inhibited ischemia-induced cardiomyocyte senescence to enhance the cardioprotective effects by regulating mitochondrial fission." (PMID 34674708, 2021). "HMGB1 is a non-histone nuclear protein that can function as a pathogenic inflammatory response in a number of conditions in the brain, including epilepsy, septic shock, ischemia, traumatic brain injury, Parkinson’s disease, Alzheimer’s disease and multiple sclerosis." (PMID 33487119, 2021). "Both HMGB1 mRNA and protein levels increased significantly at day 1 post-IRI with ischemia times of 30 min and 45 min." (PMID 32312307, 2020). "HMGB1 signaling via RAGE, specifically involving monocytes/macrophages, is known to enhance brain damage after ischemia." (PMID 32106601, 2020). "HMGB1, an endogenous ligand of TLR4, can drive the pathogenesis of inflammatory and angiogenic diseases and immune regulation, such as CNV, ischemia-reperfusion injury and hemorrhagic shock, though HMGB1/TLR4 signaling pathway." (PMID 32023953, 2020). "Undoubtedly, our results also support that HMGB-1-dependent signaling pathways are also likely to be involved in other acute injuries in the CNS such as TBI and ischemia where HMGB-1 was shown to be released from the necrotic core." (PMID 31507379, 2019). "However, while ischemia as a stimulus may activate macrophages to release the inflammatory mediator HMGB1, reperfusion may exacerbate the inflammatory response by stimulating the release of more HMGB1 into the extracellular environment and aggravating brain tissue damage." (PMID 31001089, 2019).
ischemia (continued). "A number of studies have shown that key inflammatory pathways can induce retinal damage in response to ischemia, including TLR4 and HMGB1." (PMID 30235337, 2018). "A study showed that after leukocytes infiltrated the injured kidney in a model of ischemia–reperfusion injury, they produced maladaptive IL-6 when their TLR4 receptors interacted with HMGB1 released by injured renal cells." (PMID 30197987, 2018). "Two statin molecules, atorvastatin and simvastatin, protected rat brains from ischemic injury by significantly attenuating the overexpression of HMGB1, RAGE, TLR4, and NF-κB induced in ischemia." (PMID 28127491, 2017). "Tanshinone II A (Tan IIA) markedly reduced the expression levels of HMGB1, TLR4, RAGE, and NF-κB after ischemia in rats." (PMID 28127491, 2017). "Inhibition of HMGB1 significantly suppressed the expression of NLRP3, ASC, and the maturation of caspase-1 in ischemia retinal tissue." (PMID 26224068, 2015). "When exogenous pathogen-derived chemicals stimulate the innate immune system, HMGB1 is released actively, while invasion is absent ischemia or cell injury release HMGB1 passively." (PMID 41311551, 2025). "HMGB1 is known to play a crucial role in the early stages of I/R injury by binding to RAGE and triggering the activation of pro-inflammatory pathways, leading to increased ischemia injury." (PMID 37305825, 2023). "However, it has been shown that histones and high mobility group box-1 (HMGB1), acting as DAMPS, induce NET formation, and NETs are cytotoxic to hepatocytes and pro-inflammation during liver ischemia/reperfusion (I/R) injury." (PMID 38203352, 2023). "Injured hepatic cells release damage-associated molecular patterns (DAMP), one of which is the high-mobility group box 1 (HMGB1), a ubiquitous nuclear and cytosolic protein that is passively released by ischemia or cell injury in the absence of an invasion." (PMID 36294936, 2022). "The serum levels of HMGB1 were not increased during 12 h ischemia; however, they were significantly elevated after reperfusion (P < 0.05, 12 h ischemia without reperfusion vs. 12 h I/R)." (PMID 34381442, 2021). "To determine whether social defeat stress synergizes with global ischemia to worsen HMGB1 release and whether PROG treatment can attenuate such release, we measured serum and hippocampal levels of HMGB1 on days 7 and 14 after global ischemia." (PMID 32466385, 2020). "Interestingly, two largely used cholesterol-lowering drugs, namely atorvastatin and simvastatin, significantly diminished the overexpression of HMGB1, RAGE, TLR-4, and NF-kB induced by ischemia." (PMID 32679721, 2020). "Sham-operated animals had undetectable plasma HMGB1 levels; however, a significant amount of plasma HMGB1 was detected in both the PBS-treated and scrambled siRNA-treated control groups when the livers were subjected to 60 min of ischemia and 6 h of reperfusion." (PMID 28382970, 2017). "Both HMGB1 and TLR4 promote skeletal muscle recovery after ischemia." (PMID 26744383, 2016). "In a previous study, we demonstrated that HMGB1 was released from necrotic cells in the early stage of ischemia in DM rats compared with non-DM rats." (PMID 26665003, 2015). "Electroacupuncture pretreatment at PC6 acupoints, but not at non-acupoints, inhibited this ischemia-induced increase in myocardial HMGB1 expression at all time points, at the level of both protein (PC6+IR vs. IR, p < 0.05) and mRNA (PC6+IR vs. IR, p < 0.05)." (PMID 26499847, 2015). "There is increasing evidence that extracellular HMGB1 acts as an inflammatory mediator in ischemia, hemorrhagic shock, noninfectious hepatitis, and peripheral tissue trauma." (PMID 24410860, 2014). "Previous studies have demonstrated that HMGB1 could be released from necrotic cells passively or secreted actively from immune cells or non-immune parenchymal cells, such as hepatocytes,in ischemia." (PMID 24924349, 2014).
ischemia (continued). "To determine whether stress-induced HMGB1 release primes, the NLRP3 inflammasome in rats subjected to global ischemia, and whether PROG treatment modulates stress priming, we investigated the NLRP3 inflammasome signaling pathway in the hippocampus on days 7 and 14 after global ischemia." (PMID 32466385, 2020). "On the other hand, high mobility group box 1 (HMGB1), a non-histone DNA binding protein, has been found to be passively released by the necrotic cardiomyocytes in response to ischemia and identified as a mediator of inflammation and apoptosis in MI/RI." (PMID 34859077, 2021). "Notably, in liver ischemia/reperfusion injury and non-ALD conditions, extracellular HMGB1 prominently contributes to inflammation in liver injury." (PMID 38034869, 2023). "Among the subcellular organelles, there was no merged image of HMGB1 on Rab5, Rab7, LAMP1, LC3A/B, and KDEL indicating that HMGB1 was not imported into the endosomes, phagosomes, lysosome, or endoplasmic reticulum in neurons at 6, 12, and 24 h after ischemia." (PMID 32155899, 2020).